CERS2 (ceramide synthase 2)
Diseases named in the same sentence as CERS2 in open-access papers (continued):
Sharing a sentence is not in itself a finding about the gene and the disease.
tumor (continued). "Further studies indicated CerS-2 knockdown could enhance the activity of V-ATPase and increase extracellular H+ concentration in PC-3M-2B4 cells, thus inhibiting MMP-2 and MMP-9 activation, and eventually leading to apoptosis of tumor cells." (PMID 30988071, 2019). "Data mining of our previous human HCC transcriptome dataset showed that the gene expression of CERS2, CERS4, CERS5, and CERS6 was significantly increased in HCC tumors compared with that in non-tumor adjacent tissues, while no obvious difference was observed in ASAH1 gene expression." (PMID 33803928, 2021).
cancer (26 papers, 2013 to 2024). A tumor composed of atypical neoplastic, often pleomorphic cells that invade other tissues. "Future studies are still needed to address whether CerS-2 down-regulation is a cause or consequence of the progression of most human cancers." (PMID 30988071, 2019). "We focused on LASS2 (CERS2) as it is a highly expressed gene across cancers, as well as it has a lower expression level in chemoresistant tumors than chemosensitive tumors." (PMID 38191448, 2024). "As we have observed, in different contexts, the activity of CERS2 can either promote apoptosis or inhibit it, depending on various factors, highlighting its versatile role in cancer biology." (PMID 37958652, 2023). "Bile acid, namely LCA, activated cancer-promoting genes including Cers1, Cers2, Cers5, and CERK in the cancerous HT-29 cell line in a miR125b-dependent way." (PMID 37298127, 2023). "Luminal B-specific AS of CERS2 reduces the levels of very-long-chain ceramides that allows enhanced proliferation and migration of cancer cells, and a poor prognosis outcome for patient survival." (PMID 33568634, 2021). "In contrast, overexpression of CERS2, that synthesizes very-long-chain ceramides, has been demonstrated to inhibit cancer cell proliferation and migration in prostate, breast, and bladder cancers." (PMID 33568634, 2021). "In this review, we will investigate the clinical and pathological role of CerS-2 in human malignant tumors." (PMID 30988071, 2019). "In this review, we discussed the expression, as well as the clinical and pathological significance of CerS-2 in diverse human cancers." (PMID 30988071, 2019). "Understanding of the role of CerS-2 in some cancers is still at the initial stage, warranting further investigation." (PMID 30988071, 2019). "Collectively, the information compile here should serve as a comprehensive repository of the current knowledge in this area, and would aid in the design for further studies about CerS-2 in cancers." (PMID 30988071, 2019). "Here, we observed that the levels of CERS6, responsible for the generation of C16-Cer, were as high in cancer cells and similar to the levels of CERS2 (8.7 ± 0.4) among all cell lines tested." (PMID 30206207, 2018). "It is noteworthy that pharmacological inhibition of BCL2L13 may offer the potential to increase proapoptotic ceramide levels in cancers by restoring CERS2 activity." (PMID 37958652, 2023). "In this review, we mentioned several studies that underscore the important implications that ceramides and their synthesis have in cell physiology and pathophysiology and taken together suggest that alteration of CERS2 functionality influences the development of cancer." (PMID 37958652, 2023). "Although the utility of CERS2 expression may be limited, its potential as an antimigration cancer therapeutic should be further examined." (PMID 31636736, 2019). "Moreover, we will discuss whether CerS-2 can be used as a potential predictive biomarker for cancers and a target for further cancer treatment." (PMID 30988071, 2019). "Thus, it suggested that CerS-2 expression may be correlated with the development and progression of human BC and may be a potential prognostic indicator for this cancer." (PMID 30988071, 2019). "Thus, low level of CerS-2 protein might suggest a bad prognosis and up-regulation of CerS-2 protein might act as a promising therapeutic strategy for malignant tumors." (PMID 30988071, 2019). "Taken together, these data show that targeting SK1 is a potential therapeutic strategy in cancer, enhancing oncogene-induced senescence through an increase of VLC Cer downstream of CerS2." (PMID 33414460, 2021). "Two genes closely related to cancer metastasis, called MMP-2 and MMP-9, had higher activities in BC cells knocked down for CerS-2." (PMID 30988071, 2019). "The results showed that CERS2, VAPB, GPAA1, and ST3GAL1 were widespread CNVs in pan-cancer." (PMID 36059802, 2022).
cancer (continued). "Ceramide Synthase 2 and GBA are widely acquired by CNV in various types of cancers." (PMID 35846357, 2022).
infection (5 papers, 2017 to 2023). The state of being infected such as from the introduction of a foreign agent such as serum, vaccine, antigenic substance or organism. "Our qRT-PCR data revealed that sphingolipid metabolic key genes encoding enzymes: Cers2, Gba2, Gla, Asah1, Asah2, Acer2, Acer3, Neu3, Sgpp1, and Sphk1 were robustly upregulated in mRNA levels by the infection of C. sinensis." (PMID 36339341, 2022). "According to a previous report, reduced invariant natural killer T (iNKT) cells were observed in the thymus, spleens, blood, and livers of CerS2-null mice, which rendered CerS2-null mice more susceptible to infection with a hepatotropic strain of the lymphocytic choriomeningitis virus." (PMID 33800208, 2021). "Levels of monocytes were unaltered, whereas neutrophils and CD8+ T cells were increased in CerS2-null mouse liver prior to infection, probably due to increased hepatocyte turnover." (PMID 29163475, 2017). "However, as opposed to WT and ΔCT viruses, Gag-normalized infectivities of pseudotyped viruses produced in CerS2−/− cells were more than twofold greater than the infection efficiencies of viruses from WT cells." (PMID 33515546, 2021). "Increased expression of several acute-phase reactants, such as amyloid A proteins (Saa1, Saa2, Saa3), amyloid P component serum (Apcs), haptoglobin (Hp), hemopexin (Hpx) and orosomucoid 2 (Orm2), was observed only in CerS2-null mice after transfer of iNKT cells and infection with LCMV." (PMID 29163475, 2017). "Two days post-infection (DPI) with 2 × 106 PFU of LCMV, increased levels of the virus were detected in the liver of CerS2-null mice compared to WT mice as ascertained by immunofluorescence and by viral titers." (PMID 29163475, 2017). "Differentially expressed genes that were common in both comparisons, but were not common between CerS2-null mice with and without infection, were considered to be a downstream effect of iNKT cells." (PMID 29163475, 2017). "Cultured hepatocytes from WT and CerS2-null mice did not display differences in infection excluding the possibility that altered LCMV internalization or proliferative capacity in hepatocytes is the primary cause for the enhanced susceptibility of CerS2-null mice to hepatic LCMV infection." (PMID 29163475, 2017).
metabolic disorders (2 papers, 2020 to 2023). "On the other hand, increase in LCFA‐Cer (16:0) and decreases in VLCFA‐Cer (22:0, 24:0) in obese subjects, resulting from imbalance of CerS2/6 expression and inhibition of β‐oxidation, were reported to correlate to progression of metabolic disorders." (PMID 32378734, 2020).
heart disease (1 paper, 2025). "Further, to confirm the fundamental theory that ceramide contributes to cardiac disease in vivo, we created a transgenic mouse model in which the CerS2 gene was locally and temporarily overexpressed in the heart of MHC-CerS2 mice after doxycycline administration." (PMID 40251632, 2025). "Furthermore, we used a transgenic mouse model, in which the CerS2 gene was overexpressed in the CMs of α-MHC-CerS2 mice, to validate the basic idea that ceramide contributes to heart disease in vivo." (PMID 40251632, 2025). "To confirm the initial hypothesis that long-chain and very long-chain ceramides contribute to heart disease and to examine the impact of elevated ceramide levels in the heart, we used a transgenic mouse model, where the Cers2 gene is overexpressed in the CMs of MHC-CerS2 mice." (PMID 40251632, 2025).
infectious disease (1 paper, 2021). A disorder directly resulting from the presence and activity of a microbial, viral, or parasitic agent in humans. "As ceramide synthase 2 shows the highest activity towards incorporation of C22:0 and C24:0 into ceramides, these findings are in concordance with our observation that levels of C22:0 and C24:0 show the strongest inverse association with all-cause and infectious disease mortality." (PMID 34684385, 2021).
inflammation (1 paper, 2021). Aberrant reaction of the microcirculation characterized by movement of fluid and leukocytes from the blood into extravascular tissues. "However, CerS2 null mice exhibited a significantly decreased level of IL-4 compared with WT mice during OVA-induced airway inflammation." (PMID 33800208, 2021).
CERS2 also shares sentences with these, for which no sentence is quoted: liver cancer (4 papers); thyroid cancer (3); cardiovascular disease (2); meningioma (2); non-small cell lung carcinoma (2); Type 2 diabetes (2); acute myeloid leukemia (1); adenocarcinoma (1); atrial fibrillation (1); bladder tumours (1); cardiac arrhythmia (1); cerebellar ataxia (1); cervical cancer (1); cholangiocarcinoma (1); Crohn disease (1); dementia (1); diabetic cardiomyopathy (1); diabetic kidney disease (1); diffuse large B-cell lymphoma (1); dilated cardiomyopathy (1); dyslipidaemia (1); endometrial cancer (1); esophageal carcinoma (1); fibrosis (1); gestational diabetes (1); heart failure (1); hepatoblastoma (1); hypertrophic cardiomyopathy (1); hypertrophy (1); inflammatory bowel disease (1).
A further 21 diseases each share a sentence with CERS2 in 1 paper.